HIRIP3 (HIRA interacting protein 3)
Description:
Histone chaperone that carries a H2A-H2B histone complex and facilitates its deposition onto chromatin.
Tractability: PROTAC: ubiquitination databases record sites on it; its protein half-life has been measured.
Gene: Protein-coding gene on chromosome 16 (29,992,330 to 29,996,120, reverse strand). Ensembl gene ENSG00000149929.
Subcellular location: Nucleus
Subcellular location (Human Protein Atlas): Nucleoplasm; Nucleoli
Gene Ontology:
Molecular function: H2A-H2B histone complex chaperone activity; protein binding
Biological process: chromatin organization
Cellular component: nucleolus; nucleoplasm; nucleus
Genetic constraint (gnomAD): Loss-of-function variants: 44 observed, 55.78 expected, observed/expected ratio (o/e) 0.79, 90% interval 0.62 to 1.01. The upper end of that interval is the gene's LOEUF score, 1.01, which puts it in group 4 of 6, group 1 being the genes least tolerant of losing a copy. Missense variants: 765 observed, 732.05 expected, observed/expected ratio (o/e) 1.04, 90% interval 0.98 to 1.11. Synonymous variants: 318 observed, 271.34 expected, observed/expected ratio (o/e) 1.17, 90% interval 1.07 to 1.29.
Homologues: Orthologues: chimpanzee HIRIP3 (99% identical), macaque HIRIP3 (93% identical), dog HIRIP3 (73% identical), pig HIRIP3 (70% identical), guinea pig HIRIP3 (68% identical), rabbit HIRIP3 (62% identical), rat Hirip3 (62% identical), mouse Hirip3 (58% identical), tropical clawed frog hirip3 (33% identical), zebrafish hirip3 (25% identical).
Diseases named in the same sentence as HIRIP3 in open-access papers:
HIRIP3 is named in the same sentence as 4 diseases in open-access papers, as found by Europe PMC text mining. Sharing a sentence is not in itself a finding about the gene and the disease. The quoted sentences say what the papers report.
aortic valve stenosis (2 papers, 2025). Aortic valve stenosis (AVS) is a condition characterized by narrowing of the heart's aortic valve opening. "Previous research identified HIRIP3 as a gene linked to aortic valve stenosis, suggesting its role in cardiac development." (PMID 40547214, 2025). "Previous research has identified HIRIP3 as a candidate gene associated with aortic valve stenosis." (PMID 40176795, 2025).
cardiovascular malformations (2 papers, 2022 to 2025). "Research involving fetuses with recurrent microdeletions at the 16p11.2 locus has shown that the second HIRIP3 allele lacks additional mutations, implying that haploinsufficiency of HIRIP3 may contribute to cardiovascular malformations." (PMID 40176795, 2025). "In the cardiovascular malformations associated with 16p11.2 microdeletion syndrome, our research found that 32% (8/25) of microdeletion regions of cardiovascular malformations contain TBX1, GJA5, HIRIP3, and other genes." (PMID 36553582, 2022).
diabetes (1 paper, 2025). "Given the intertwined nature of cardiovascular health and diabetes-related complications, further investigation into HIRIP3’s role in DR and CHD is essential." (PMID 40176795, 2025). "HIRIP3 emerges as a novel therapeutic target, and understanding its contribution to these diseases could unveil shared molecular pathways, thereby facilitating the development of targeted therapies to mitigate the risks associated with diabetes and its complications." (PMID 40176795, 2025).
HIRIP3 also shares sentences with these, for which no sentence is quoted: Alzheimer disease (1 paper).